TNF (tumor necrosis factor)
Diseases named in the same sentence as TNF in open-access papers (continued):
Sharing a sentence is not in itself a finding about the gene and the disease.
infection (continued). "We previously observed that TNF-α (a key pro-inflammatory cytokine) enhanced susceptibility of other myeloid cells (monocyte-derived dendritic cells, moDC) to infection with several virulent, but not attenuated, ASFV isolates." (PMID 36298767, 2022). "Moreover, it rapidly reduced the expression of IL-10 in the later stage with the decline of IL-1β, IL-6, TNF-α, and IFN-γ, to prevent the continuously excessive release of IL-10 from causing severe immune suppression and uncontrollable infection." (PMID 35071595, 2022). "Moreover, we found that the protein levels of IL1B, IL6, and TNF showed a significant and time-dependent increase accompanying infection." (PMID 35794518, 2022). "In contrast, TNF-α production was significant only with conidial infection." (PMID 35628694, 2022). "Infection of airway epithelial cells by SARS-CoV-2 causes cytological damage by activating the local immune response, releasing proinflammatory mediators such as IFNγ, IL-1β, IL-6, TNF-α." (PMID 36012968, 2022). "In addition, no significant alteration in the levels of IFNγ, IL-1β, IL-4, IL-6, IL-8, IL-10, CXCL10, and TNFα was observed in peripheral blood after Vir-S74-T3Bo infection by comparing Att-S74-T3Bo-inoculated and naïve control animals." (PMID 36466866, 2022). "While infection with strain Nine Mile I rendered the cells partially refractory to re-stimulation with E. coli lipopolysaccharide, Cb30/14 exerted a selective suppressive effect which was restricted to IL-6 and TNF-α and spared IL-1β." (PMID 36558755, 2022). "Moreover, SEP attenuated the MPO level in the lung and inflammatory cytokines IL-1β, TNF-α, IL-6 in the peritoneal macrophage during infection." (PMID 35370674, 2022). "However, the protein levels of TNFα in all infected groups were inhibited, and the inhibitions of TNFα in the coinfection groups were slightly stronger compared with single infections." (PMID 35457287, 2022). "Release of cytokines, such as IFN-γ and TNF-α, activated the NK cells help coordinate a broader immune response, including the recruitment of macrophages and neutrophils at the site of cancer, infection, or senescent cells." (PMID 35326467, 2022). "Moreover, CD49a+ NK cells produce high levels of proinflammatory cytokines, such as IFN-γ and TNF-α, and infection alters their expression in stimulated CD49a+ NK cells." (PMID 36206304, 2022). "Notably, throughout the 24-h course of M28ΔtatA infection, the expression trends of the TNF-α, IL-6 and inducible nitric oxide synthase (iNOS) genes were in line with the ELISA results." (PMID 34195100, 2021). "Cells were primed with TNFα for 30 min before the infection." (PMID 34320039, 2021). "In the non-CF mice, there is a visual elevation of all analytes at 48 h, though only two of five measured cytokines, IL-6 and TNF-α, were significantly elevated (p = 0.002, p = 0.049 respectively), and remained elevated 2 weeks post infection (p = 0.010, p = 0.044)." (PMID 34475490, 2021). "This likely reflects the importance of low-level or temporally and spatially isolated expression of TNF-α in mediating the response to infection, and the pathological effects of TNF-α may primarily result from its overproduction." (PMID 34696354, 2021). "Previous clinical studies demonstrated that IFN-ɣ treatment could restore monocytic HLA-DR expression, the secretion of TNF-α upon ex vivo LPS stimulation, and reduce infection-related mortality." (PMID 34312428, 2021). "Based on the central role of pro-inflammatory cytokines in the anti-Ct response, we hypothesized that Ct infection would increase the expression of pro-inflammatory cytokines such as IL-6, IL-8, and TNF-α." (PMID 34684219, 2021). "Interestingly, GL pretreatment effectively decreased the upregulation of pro-inflammatory cytokines (IFN-γ, TNF-α, and IL-6) induced by ST infection in spleen and liver, and increased secretion of anti-inflammatory cytokine IL-10 in spleen." (PMID 34239908, 2021).
infection (continued). "TNF-α is secreted by macrophages, natural killer cells, endothelial cells, and fibroblasts, and induces the proinflammatory cytokines IL-1β and IL-6, which are involved in innate immunity in the early stages of infection." (PMID 34884507, 2021). "In addition, M. tuberculosis-infected mice injected with EVs from M. tuberculosis-infected macrophages showed heightened production of TNF-α and recruitment of immune cells to the infection site to control bacterial replication." (PMID 34638604, 2021). "The patterns of response of some cytokines, such as IFN-γ and IL-12p70, were most abnormal for infection in BS0–II disease, whereas for others, such as IL-10 and TNF-α, the relationships between cytokines and markers of perfusion were most abnormal for infection in BSV–VI disease." (PMID 33723589, 2021). "Previous studies with anti-TNFα monoclonal antibodies have not shown benefit due to the increased risk of infection and possibly due to the removal of a regenerative signal provided by TNFα." (PMID 34763711, 2021). "Moreover, virus mixed infection enhanced the mRNA expressions of TNF-α, IL-1β, IL-6, IL-10, IFN-α, and IFN-β by 2–170 times." (PMID 33827620, 2021). "Not all studies concur, but recent scRNAseq evidence suggests that IFN-I, along with IL-1- and TNF-dependent pathways may be particularly important in severe infection." (PMID 33442686, 2021). "TNF-/- mice exhibited greater severity and pathology upon infection relative to WT mice." (PMID 34777390, 2021). "Our data showed that the levels of IL-6, IL-8, and TNF-α secreted by macrophages significantly increased after infection with C. glabrata, although they were lower than those reported for C. albicans infection, which is in consistence to report in previous work." (PMID 33680221, 2021). "In addition, we found a sustained upregulation of multiple inflammatory transcripts in iron-loaded FthΔ/Δ mice as early as 12 hours after infection and the resultant massive overproduction of the key proinflammatory cytokines IL-1β, IL-6, and TNF-α." (PMID 34236052, 2021). "Similarly, TNF+ CD8+ T cells seemed to arise at 90 h post-infection, particularly in the C-strain vaccinated animals." (PMID 34445493, 2021). "TNF-α is one of the reasons for the destruction of the immune defense during infection." (PMID 34490839, 2021). "Indeed, plasma was analysed several days after symptom onset and TNF-α, a component of the acute-phase response, is known to be produced at earlier time points after infection." (PMID 33439360, 2021). "Importantly, following the infection of NTSNΔinlF, there was significantly higher expression of TNF-α in the liver (p <0.001)." (PMID 35223532, 2021). "Inflammatory cells infiltrate the sites of infection at an early stage of the infection with SARS-CoV2 and cause a stormy release of pro-inflammatory cytokines like IL-6, IL-17A, TNFα, IFNγ, IL-1α/β, and chemokines like CC-chemokine ligand 2 (CCL2) as well as CXC-chemokine ligand 10 (CXCL10)." (PMID 33643316, 2021). "Upon infection with A. phagocytophilum, a similar finding was made for TNF." (PMID 33747981, 2021). "Tumor necrosis factor is a key mediator for the activation and recruitment of inflammatory cells, including polymorphonuclear neutrophils (PMNs) and macrophages, to sites of infection, and is as such involved in infection control, tissue repair and healing." (PMID 35264975, 2021). "Similarly, PAR1ΔCM mice had a significant increase in CVB3 genomes and TNF-α mRNA expression in their hearts compared with control mice 8 days after infection." (PMID 34253819, 2021). "Similarly, human neutrophil-recruiting cytokines such as TNF and IL-8 were also produced by the human endothelium upon infection." (PMID 34315900, 2021).
infection (continued). "We found that infection with M. mulieris significantly elevated multiple proinflammatory markers (IL-6, IL-8, TNF-α and MCP-1) and altered metabolites related to energy metabolism (nicotinamide and succinate) and oxidative stress (cysteinylglycine, cysteinylglycine disulfide and 2-hydroxygluatrate)." (PMID 35004344, 2021). "We observed that TNF treatment shortened the time interval between infection and death." (PMID 34016976, 2021). "However, during an infection, upon entry of moDCs to the site of infection, the moDCs produce TNF-α and an inducible nitric oxide synthase (iNOS), which eventually confers innate protection." (PMID 34360810, 2021). "Our panel showed positive IFN-β, IL-12A, IL-1β and TNF-α immunostaining in the tissues of squirrel monkeys, demonstrating a similar profile in the nervous tissues of the newborns in G1, who were born after maternal infection." (PMID 33731800, 2021). "The expression of cytokines (IL-1β and TNF-α) as a vital part of the immune system is modulated by infection or inflammation, so assessing their expression levels may help explain the mechanisms of specific contaminants’ toxicity." (PMID 34062969, 2021). "For example, infection-induced levels of TNF-α, IL-1β, and IL-17A were higher in the sera of pregnant mice than in the sera of virgin control mice, which parallels their increased bacterial burden, whereas the anti-inflammatory cytokine IL-10 peaked to higher levels in virgin than in pregnant mice." (PMID 33622714, 2021). "Our study shows that in utero exposure to anti-TNF-α and/or thiopurine does not increase the risk of an antibiotic-treated infection or hospital admission because of a severe infection in children during their first 5 years of life." (PMID 33046558, 2021). "Importantly, the IL-4 environment can also significantly impact the quality/avidity of T cell immunity, where IL-4R⍺ expression was inversely related to IFN-γ and TNF expression on effector T cells following infection/vaccination." (PMID 34006897, 2021). "Similarly, TNF-α production was detectable as early as 4 hr, and rapidly peaked at 18 hr, and subsequently showed a slight falling trend up to day 5 post infection." (PMID 34912336, 2021). "To confirm that IAP inhibitor, Debio 1143, was utilizing the TNF pathway to cause apoptosis in HBV-infected cells, TNF−/− and C57Bl/6 mice were infected with HBV 1.0 mer (genotype D3) and one week after infection we commenced a 2-week treatment course with daily oral Debio 1143 or vehicle." (PMID 34162831, 2021). "Bacterial infection studies in mammalian models showed that TNF–α deficiency caused an increased bacterial burden in L. pneumophila infected mice, and inhibition of TNF–α reduced NO and ROS production and promoted the infection of Mycobacterium tuberculosis and Brucella abortus." (PMID 34439908, 2021). "Finally, fish that received SSWE intraperitoneally before infection with Phdd exhibited elevated expression of Th1-type cytokines, namely, IL-8, IL-12, TNF-α, and IFN-γ." (PMID 35140710, 2021). "Indeed, the average concentrations of TNF-α and IP-10 were significantly different between early and late infection groups." (PMID 33921604, 2021). "Regarding protective immunity, NMII infection induces toll-like receptor 4-independent dendritic cell maturation with high IL-12 and TNF production, implying that NMII might activate dendritic cell-mediated T-cell response in the host." (PMID 34795669, 2021). "If we observe the cytokine profiling of the infectious state, TNFα shows a constant 2–3 fold change which symbolizes its role in the parasite clearance during initial infection but the fold change of IL12 (2–5 fold change) is low as compared to the fold change of IL10 (7–8 fold change)." (PMID 35011356, 2021). "Similarly, there was a delayed increase in the percentage of Mtb-specific CD4+TNF-α+T cells in the high dose infection group with a higher percentage of this subset observed at week 3 post-infection." (PMID 34484203, 2021).
infection (continued). "We selected IL-6, IL-8, and TNFα as their production was markedly enhanced post-infection." (PMID 34367171, 2021). "Furthermore, Dnmt3bfl/flSpCcre and control mice showed similar CXCL5, CCL20, IL-1β and TNF-α BALF levels upon infection with PAK." (PMID 33793661, 2021). "could provoke the activation of T cells, monocytes/macrophages, and natural killer (NK) cells, which have important roles in the production of pro-inflammatory cytokines such as TNF-α, IL-6 and IL-1, particularly during the acute phase of infection." (PMID 34666703, 2021). "CSFV-infected alveolar macrophages can also secrete up to 1 ng/mL TNF at 16 h after infection." (PMID 34696447, 2021). "Interleukin (IL)-17, IFN-γ, TNF-α, and IL-10 may be critical to the host survival and infection control." (PMID 34869064, 2021). "The response to an infection triggers the activation of different responsive cells and the production of signalling molecules, especially pro-inflammatory cytokines such as tumour necrosis factor (TNF)-α, interleukin (IL)-1 and IL-6." (PMID 34573721, 2021). "The levels of TNF-α mRNA were elevated ~10-fold in the lungs on days 1 and 3 after infection." (PMID 33477869, 2021). "However, at sites of infection, the neutrophil lifespan increases due to the high levels of inflammatory cytokines, such as IL-1, TNFα, IL-6 and G-CSF, present in the local tissue environment." (PMID 33571211, 2021). "(2008) demonstrated that TNF- is needed to regulate B. pseudomallei infection in a mouse model, in which the mice were more inclined to infection with increased number of bacterial in the spleen and liver, with elevated mortality rates in TNF-/, TNFR1, and TNFR2/mice." (PMID 34456925, 2021). "A high dose infection caused a significantly higher TNF-α response in the CD8+ T cells at 3 weeks post-infection but no noticeable changes in the IFN-γ response this early in infection." (PMID 34484203, 2021). "Interleukin-10 and TNF-α in infected cells increased relative to uninfected AMs in all treatment groups including the control foals, suggesting an age-related increase in response to infection." (PMID 33510265, 2021). "Similarly, Mtb-specific CD8+TNF-α+T cells exhibited a significant increase in the high dose group at 3 weeks post-infection compared to the low dose infection group." (PMID 34484203, 2021). "Additionally, we demonstrated elevated mRNA levels of IL1β and TNFα at the later stage of infection (28dpi)." (PMID 34899715, 2021). "Infection leads to rapid upregulation of pro-inflammatory cytokines such as TNF-α, IL-6, and INFγ." (PMID 34696354, 2021). "Similar to other intracellular pathogens, T-lymphocyte-derived cytokines activate macrophages, especially those that respond to Th1, such as interleukin (IL)-12, IFN-γ, and tumor necrosis factor (TNF)-α, which are important cytokines for host defense against TM infection." (PMID 34234782, 2021). "In addition, infection with P. gingivalis also up-regulates the ROS/NF-κB p65 signaling pathway, leading to the expression of IL-1β and TNF-α." (PMID 34831265, 2021). "Moreover, infection of B.1.1.7 and B.1.351 resulted in significant elevation of several key inflammatory cytokines in K18-hACE2 mice, including TNF-α (lung), IL-1β (lung), IL-6 (lung and liver), IL-13 (liver), IFN-α (liver) and IFN-β (liver)." (PMID 34772941, 2021). "In the course of an infection, NETs production is triggered not only by microorganisms, but also by various pro-inflammatory mediators: tumor necrosis factor alpha (TNF-α), interleukin-8 (IL-8), nitric oxide, activated platelets, activated endothelial cells, and a large panel of auto-antibodies." (PMID 34445556, 2021). "Therefore, infection screening process prior to IA TNF therapy should be similar to that of systemic therapy." (PMID 34525992, 2021). "Notably, the expression of IL-8 and TNF-α was upregulated hundreds of times at both 12 h and 24 h post-infection of HPS4-YC." (PMID 34674760, 2021).
infection (continued). "Cytokines are released during systematic inflammation due to surgical stress, infection, and inflammation of the blood vessel itself, and inflammatory cytokines such as IL and tumor necrosis factor stimulate AM production and secretion from vascular smooth muscle cells." (PMID 34179545, 2021). "Prior to infection, DP T cells showed higher TNF-α, IL-10, MIP-1β, and IL-22 expression than traditional CD4 and CD8 T cells, suggesting that these cells may potentially perform a non-specific function in the pulmonary immune response." (PMID 34929014, 2021). "MyD88-dependent signaling triggers the activation of NF-κB, a transcription factor associated with inflammation, which produces proinflammatory cytokines such as tumor necrosis factor (TNF)-α and IL-6, which in turn induces a defense response against infection." (PMID 34684874, 2021). "(C) The level of IL-12/23 p40 and IL-10 didn’t change with the change of intracellular CFU (P<0.05), while the level of TNF-α and IL-6 increased with the intracellular CFU decreasing, and the increase level of TNF-α was lower than that of the infection group (P<0.05)." (PMID 35003120, 2021). "We hypothesize that proinflammatory cytokines (TNF, IL-1, IL-6) play an essential role in promoting chemokine production during early infection because these inflammatory cytokines are usually decreased at the late phase." (PMID 34368012, 2021). "Lastly, trimeric membrane-associated TNF-α was found in the T cells (CEM) treated with EVs from the HIV-1-infected cells released at 24 h (lane 7), which is suggestive of activation of the TNF pathways, possibly due to infection." (PMID 33916140, 2021). "There are reports suggesting that EV-A71 strain ATCC VR-784 infection could trigger RD-A cells to release of TNF-α at 5 MOI, with a significant increase at 20 and 32 hpi24." (PMID 34493781, 2021). "After 12 h, the relative expression of TNFα, iNOS, IL-1β, and IL-18 in the ΔhtpG infection group was significantly lower than that in the WT infection group (p < 0.01), and the relative expression of IL-1β and IL-18 was extremely lower than that in the CΔhtpG infection group (p < 0.01)." (PMID 34869065, 2021). "Thus, the percentages of CD4+IFN-γ+ and CD4+ TNF-α+T cells were significantly lower in the high dose group compared to the low dose group at week 1 post-infection." (PMID 34484203, 2021). "Furthermore, both TNF-α and IL-17 can regulate chemokine-expression and thereby modulate the recruitment and maintenance of immune cells, including T-cells, at the site of infection." (PMID 33679802, 2021). "Infection of macrophages with HIV-1 is reported to induce TNF-α expression." (PMID 33762317, 2021). "Here, we addressed the role of the DUB OTU domain aldehyde binding-1 (OTUB1) in hepatocyte cell death upon both infection with the hepatocyte-infecting bacterium Listeria monocytogenes (Lm) and D-Galactosamine (DGal)/Tumor necrosis factor (TNF)-induced sterile inflammation." (PMID 33712742, 2021). "PFO is speculated to induce intravascular hemolysis and the production of proinflammatory cytokines, such as TNF-α, IL-5, IL-6, and IL-8 beginning in the early stage of infection in hosts infected with C. perfringens." (PMID 34385995, 2021). "Similarly, the present meta-analysis observed that the odds of serious infection were 1.72 times higher in the anti-TNFα agent treatment group (95% CI: 1.56–1.90, p < 0.00001)." (PMID 34790122, 2021). "As importantly, it discovers an aspect of TNF signaling that is essential for intact transcription of TNF-target genes, thereby contributing to the decision between cell death and survival, auto-inflammation, or an efficient response to infections." (PMID 34663829, 2021). "Furthermore, a previous study showed the increase in TLR2 and TNF-α as the host immune responses to the infection of B. abortus through the host immune response to pathogen infection." (PMID 33829052, 2021).